FCRLA (Fc receptor like A)
Description:
May be implicated in B-cell differentiation and lymphomagenesis.
Synonyms: FcRX; FCRL; FCRLM1; FREB; MGC4595; FCRLc2; FCRLb; FCRLc1; FCRLd; FCRLe; FCRLX
Tractability: Antibody: UniProt predicts a signal peptide or a membrane-spanning region. PROTAC: its protein half-life has been measured.
Gene: Protein-coding gene on chromosome 1 (161,706,958 to 161,714,352, forward strand). Ensembl gene ENSG00000132185.
Subcellular location: Cytoplasm
Gene Ontology:
Molecular function: transmembrane signaling receptor activity
Biological process: cell surface receptor signaling pathway; immune response
Cellular component: cytoplasm; external side of plasma membrane
Genetic constraint (gnomAD): Loss-of-function variants: 26 observed, 30.46 expected, observed/expected ratio (o/e) 0.85, 90% interval 0.62 to 1.18. The upper end of that interval is the gene's LOEUF score, 1.18, which puts it in group 5 of 6, group 1 being the genes least tolerant of losing a copy. Missense variants: 422 observed, 455.54 expected, observed/expected ratio (o/e) 0.93, 90% interval 0.86 to 1. Synonymous variants: 174 observed, 177.94 expected, observed/expected ratio (o/e) 0.98, 90% interval 0.86 to 1.11.
Homologues: Orthologues: chimpanzee FCRLA (99% identical), macaque FCRLA (96% identical), dog FCRLA (74% identical), pig FCRLA (74% identical), guinea pig FCRLA (74% identical), rabbit FCRLA (70% identical), mouse Fcrla (67% identical), rat Fcrla (66% identical). Paralogues in human: FCRLB (28% identical), FCGR1A (28% identical), FCRL5 (28% identical), FCRL6 (28% identical), FCRL3 (26% identical), FCRL4 (25% identical), FCRL2 (21% identical), FCGR2B (17% identical), FCGR2C (17% identical), FCER1A (16% identical), FCGR2A (16% identical), FCGR3A (15% identical), and 5 more.
Diseases named in the same sentence as FCRLA in open-access papers:
FCRLA is named in the same sentence as 38 diseases in open-access papers, as found by Europe PMC text mining. Sharing a sentence is not in itself a finding about the gene and the disease. The quoted sentences say what the papers report.
lymphoma (5 papers, 2021 to 2024). A malignant (clonal) proliferation of B- lymphocytes or T- lymphocytes which involves the lymph nodes, bone marrow and/or extranodal sites. "Fc receptor-like A is selectively expressed in B cells and may be involved in their differentiation and the development of lymphomas." (PMID 34422829, 2021). "FCRLA (Fc receptor-like A) belongs to a family of Fc receptor like-molecules, and has been identified as a B cell-specific protein and may be involved in the development of lymphomas." (PMID 35846149, 2022).
B-cell lymphoma (3 papers, 2016 to 2022). "FCRLA has been shown to be a potential target gene in immunotherapy for B-cell lymphoma." (PMID 34395521, 2021). "Furthermore, studies showed that cell surface FCRLA failed to bind extracellular Ig (Wilson 2010, Santiago 2011), suggesting this protein may be unstable when expressed on the cell surface, and could be involved in the development of B-cell lymphomas." (PMID 27446638, 2016).
ovarian carcinoma (3 papers, 2021 to 2024). A malignant neoplasm originating from the surface ovarian epithelium. "FCRLA has been confirmed to be related to the immune status and better prognosis of ovarian cancer." (PMID 35846149, 2022). "In addition, FCRLA has been shown to participate in immune response‐related pathways in various malignancies, including advanced laryngeal cancer, hepatocellular carcinoma, and ovarian cancer, hepatocellular carcinoma and ovarian cancer." (PMID 39108036, 2024). "In our study, we combined TMB and TIME evaluation methods to identify a set of genes related to the immune status of ovarian cancer, including CXCL13, FCRLA, MS4A1, and PLA2G2D." (PMID 34395521, 2021).
lung adenocarcinoma (2 papers, 2022 to 2025). A carcinoma that arises from the lung and is characterized by the presence of malignant glandular epithelial cells. "For example, an elevated expression of FCRLA in lung adenocarcinoma, among other genes, was associated with a better response to immunotherapy." (PMID 35329826, 2022).
lung carcinoma (2 papers, 2021 to 2025). "FCRLA expression in lung cancer cells was knocked down using siRNA to further verify the specific effects of FCRLA on lung cancer cells." (PMID 40881693, 2025). "FCRLA and CD79A were highly expressed in lung cancer cells, whereas RASGRP2 was expressed at low levels." (PMID 40881693, 2025). "To facilitate clinical application, in the lung cancer transcriptome, including 19,464 protein-coding genes, we extracted the three most relevant genes of B cell (CD19, TLR10, and FCRLA) and DC1 (ITGB2, LAPTM5, and SLC7A7), respectively." (PMID 34422829, 2021).
primary immunodeficiency (2 papers, 2021 to 2024). "Interestingly, CXCL13, FCRLA, and PLA2G2D were also associated with primary immunodeficiency." (PMID 34395521, 2021).
colorectal cancer (1 paper, 2025). A primary or metastatic malignant neoplasm that affects the colon or rectum. "FCRLA is a prognostic gene in malignant tumors, such as ovarian, breast, and colorectal cancer." (PMID 40881693, 2025).
laryngeal squamous cell carcinoma (1 paper, 2022). A squamous cell carcinoma that arises from the larynx. "FCRLA was also found to be associated with the expression of CD19, CD20 and prognosis of laryngeal squamous cell carcinoma." (PMID 35846149, 2022).
melanoma (1 paper, 2021). A malignant, usually aggressive tumor composed of atypical, neoplastic melanocytes. "Moreover, we also found that the high expression levels of CXCL13, FCRLA, MS4A1, and PLA2G2D were positively associated with the better response of melanoma patients treated with anti-PD1 and anti-CTLA4." (PMID 34395521, 2021). "Our results showed that the CXCL13, FCRLA, MS4A1, and PLA2G2D were positively correlated with the level of CTL infiltration in the melanoma patients treated with anti-PD-L1 or anti-CTLA4." (PMID 34395521, 2021).
periodontitis (1 paper, 2021). An acute or chronic inflammatory process that affects the tissues that surround and support the teeth. "Four common crosstalk genes between periodontitis and DS were acquired, i.e., CD19, FCRL5, FCRLA, and HLA-DOB, of which the latter had the highest prediction accuracy." (PMID 34545294, 2021).
renal cell carcinoma (1 paper, 2024). "Our study aims to investigate the mechanisms through which Fc receptor‐like A (FCRLA) promotes renal cell carcinoma (RCC) and to examine its significance in relation to tumor immune infiltration." (PMID 39108036, 2024).
cancer (6 papers, 2020 to 2025). A tumor composed of atypical neoplastic, often pleomorphic cells that invade other tissues. "This study represents the first exploration of FCRLA's biological role in malignant tumors, expanding beyond previous research focused on its immunological implications." (PMID 39108036, 2024). "Among them, 8 of 12 hub genes (EPHX3, SPINK7, FCRLA, MASP1, ZNF541, CD5, BEST2, ZAP70) seemed to be cancer-promoting genes as they were downregulated in the high-risk group." (PMID 35846149, 2022).
tumor (5 papers, 2021 to 2025). "Based on the association between the risk score and the tumor immune microenvironment revealed by the immune infiltration analysis, the role of mitochondrial dysfunction in LUAD cells and its relationship with FCRLA expression were further explored." (PMID 40881693, 2025). "The effects of FCRLA knockdown on tumor cell proliferation, apoptosis, mitochondrial morphology, and mitochondrial membrane potential were studied." (PMID 40881693, 2025). "FCRLA promoted the malignant biological behavior of RCC cells through the pERK1/2/‐MMP2 pathway and was associated with tumor immune microenvironment in RCC." (PMID 39108036, 2024). "First, experimental validation was limited to in vitro cell models, and the in vivo effects of FCRLA knockdown on tumor growth and necrosis remain unclear." (PMID 40881693, 2025). "Additionally, the correlation between FCRLA and immune checkpoints was investigated, revealing its potential role in regulating the tumor immune microenvironment." (PMID 40881693, 2025). "The ESTIMATE algorithm was employed to evaluate the association of FCRLA with tumor stromal cells and tumor immune cells, which may provide a new reference for immune therapy due to the enrichment of FCRLA in tumor stromal cells and immune cells." (PMID 39108036, 2024). "Our results similarly indicate that higher FCRLA expression may lead to increased stromal cell infiltration in the tumor microenvironment of RCC patients, contributing to poor prognosis." (PMID 39108036, 2024). "Aberrant FCRLA expression can promote malignant biological behaviors of RCC, with suppression of tumor cell apoptosis in an MMP2‐dependent manner." (PMID 39108036, 2024). "FCRLA promotes the proliferation, migration, and invasion of RCC cells and inhibits tumor cell apoptosis." (PMID 39108036, 2024). "As a downstream target of FCRLA, MMP2 may provide valuable insights into the regulation of the RCC tumor microenvironment." (PMID 39108036, 2024). "Moreover, we found that IBC tumour-infiltrating B cells also presented high levels of immature signals, which was reflected mainly in the significantly high expression of five molecules, CD22, FCRL1, FCRLA, HVCN1, and SP100, in IBC tumour-infiltrating B cells." (PMID 40624675, 2025). "Our results demonstrated that CXCL13, FCRLA, MS4A1, and PLA2G2D have a negative correlation with tumor purity in OC." (PMID 34395521, 2021).
immune disorders (4 papers, 2016 to 2024). "The TIDE algorithm further suggested that FCRLA might influence RCC progression through immune dysfunction and immune exclusion mechanisms, which are critical factors in poor immunotherapy outcomes." (PMID 39108036, 2024).
FCRLA also shares sentences with these, for which no sentence is quoted: autoimmune disease (3 papers); Graves disease (3); autoimmune thyroid disease (2); Autoimmunity (2); infection (2); AIDS (1); Behçet's disease (1); breast carcinoma (1); coronary aneurysm (1); endometriosis (1); Graves’ Orbitopathy (1); heart failure (1); hepatocellular carcinoma (1); hyperthyroidism (1); Immunodeficiency (1); infectious disease (1); Infertility (1); leukemia (1); multiple myeloma (1); nephritis (1); rheumatoid arthritis (1); thyroid (1); thyrotoxicosis (1); toxic nodular goiter (1).